WFDC2 (WAP four-disulfide core domain 2)
Diseases named in the same sentence as WFDC2 in open-access papers (continued):
Sharing a sentence is not in itself a finding about the gene and the disease.
tumor (344 papers, 2006 to 2026). "Low WFDC2 expression correlates with increased tumor mutational burden and neoantigen load and negatively correlates with immune-related gene expression." (PMID 40723266, 2025). "Although these associations point to a role for WFDC2 in tumor biology, particularly in modulating immune responses, its function during ICI therapy remains unclear." (PMID 40723266, 2025). "Notably, greater increases in WFDC2 levels were associated with tumor progression, shorter OS, and shorter PFS." (PMID 40723266, 2025). "Associations between WFDC2 expression changes and overall survival (OS), progression-free survival (PFS), and tumor progression were assessed." (PMID 40723266, 2025). "This cellular evidence provides mechanistic insights into the potential role of WFDC2 in shaping the immunosuppressive tumor microenvironment." (PMID 40723266, 2025). "Among the 58,810 cells analyzed, one tumor cell cluster characterized by high WFDC2 expression was identified." (PMID 40723266, 2025). "Publicly available transcriptomic datasets were analyzed to compare WFDC2 mRNA expression in normal and tumor tissues across various cancer types." (PMID 40727473, 2025). "To compare WFDC2 mRNA levels between normal and tumor tissues across various cancer types, we analyzed publicly available data from the TNMplotter database." (PMID 40727473, 2025). "In LUAD, WFDC2 protein and mRNA levels are significantly higher in tumor tissues than in normal tissues, and high WFDC2 expression correlates with improved overall survival (OS)." (PMID 40723266, 2025). "We analyzed tumor cells from 10 patients with LUAD brain metastasis (BrM), and discovered WFDC2 mRNA level was also higher in tumor cells compared to other cells of BrM tumor." (PMID 38304432, 2024). "Single cell RNA-seq data showed that circulating tumor cell (CSF-CTCs) from seven NSCLC-LM patients (P1, P2, P4, P6, P7, P-A and P-D) had higher level of WFDC2 mRNA (encoding HE4) than CSF immune cells." (PMID 38304432, 2024). "The analysis of WFDC2 expression in different tumors using the UALCAN database revealed pan‐cancer results indicating expression of WFDC2 mRNA levels in a variety of tumor tissues." (PMID 38742362, 2024). "Multivariate modelling, including all proteins independent of their association in the univariate analysis, identified a model for separating benign conditions from malign tumours (stage I–IV) consisting of three proteins; WFDC2, KRT19 and RBFOX3." (PMID 39068297, 2024). "WFDC2 can be measured as a tumor marker in Japan, and thus, GDF15 was excluded and WFDC2, CHI3L1, and KRT19 were used as the variables of classification." (PMID 36331721, 2023). "WFDC2 has been shown to play vital roles in tumorigenesis, chemoresistance, and tumor metastasis and was confirmed to promote tube formation and enhance angiogenesis through STAT3 signaling (PMID: 32444701)." (PMID 35924143, 2022). "For example, EOC has a large number of potential tumor biomarkers, including CA-125, WFDC2 (HE4) protein, and serum mesothelin." (PMID 33816311, 2021). "We found that WFDC2 was an oncogene in several cancers using the Oncomine database, but as a tumor suppressor in PCa, which was proven by ten independent datasets." (PMID 32678075, 2020). "Peritoneal disseminated tumors had been observed in 8 of 10 mice in the negtive control group group, while only 3 mice in WFDC2 knockdown group were found to have tumor metastases." (PMID 28679402, 2017). "We also proved that WFDC2 affected tumor growth in the presence of high-dose estrogen through gene expression regulation, although further work on the specific mechanism is needed." (PMID 26928556, 2016). "The elevated WFDC2 expression in LUAD may indicate a tumor microenvironment (TME) more responsive to therapeutic interventions, potentially explaining the improved survival observed in this subgroup." (PMID 40727473, 2025).
tumor (continued). "Elucidating these mechanisms will be essential to understand whether WFDC2 directly drives immune resistance or serves as a biomarker of broader tumor adaptation." (PMID 40723266, 2025). "Further studies with larger, stage-stratified cohorts are needed to clarify whether WFDC2 levels correlate with cancer progression or reflect tumor burden in a stage-dependent manner." (PMID 40727473, 2025). "The transient versus sustained patterns of WFDC2 elevation might reflect distinct biological responses, where transient increases could indicate effective immune activation or tumor control, while sustained elevation may signal ongoing resistance to ICI." (PMID 40723266, 2025). "Furthermore, WFDC2 enhances PD-L1 expression in both tumor cells and macrophages, thereby facilitating immune evasion by impairing the function of immune effector cells." (PMID 40727473, 2025). "Further functional studies are needed to clarify whether WFDC2 directly promotes these resistance mechanisms or serves as a downstream marker of broader tumor adaptation." (PMID 40723266, 2025). "WFDC2 levels increased significantly after treatment initiation, and greater increases correlated with worse overall survival, progression-free survival, and tumor progression." (PMID 40723266, 2025). "Following this, we used the Kaplan-Meier Plotter to analyze the relationship between WFDC2 mRNA expression levels in tumor tissues and OS, utilizing data from three comprehensive databases: The Cancer Genome Atlas (TCGA), Gene Expression Omnibus (GEO), and European Genome-phenome Archive (EGA)." (PMID 40727473, 2025). "In this study, although we initially planned to directly compare plasma WFDC2 levels and WFDC2 expression in tumor tissues assessed by immunohistochemistry (IHC), we were unable to perform this analysis due to an insufficient number of available tumor tissue samples." (PMID 40727473, 2025). "Additionally, WFDC2 has been implicated in activating the TGF-β signaling pathway, a key mediator of fibrosis and immune suppression in the tumor microenvironment." (PMID 40723266, 2025). "Interestingly, WFDC2 was a member of the red module, which was highly negatively correlated with tumor percentage (%)." (PMID 32678075, 2020). "However, it was the downregulation of the tumor suppressor genes P21 and HTRA, which led us to question the pathophysiological role of WFDC2 in tumor initiation and progression." (PMID 26928556, 2016). "We recently showed that WFDC2 is expressed in a number of normal human tissues outside of the male reproductive system, including the trachea, lung and nasal epithelium and is also found in a subset of pulmonary epithelial-derived tumour cell lines." (PMID 16600032, 2006). "Furthermore, we used tSNE to visualize tumor cells and the expression levels of WFDC2 and PAX8." (PMID 39773329, 2025). "The TNM stage of patients may be easy to obtain, while the acquisition of another predictor (risk score) required knowledge of the expression of four immune-related genes (MAL, MS4A1, OAS1, and WFDC2) in tumor tissues, which undoubtedly increased the burden of nomogram application." (PMID 32850406, 2020). "Among the genes with significant differences, NAPSA, MUC1, WFDC2, and MYO6 were well correlated with Tumor_C1 and Unknow_C2 (cells with a high positive rate of tumor markers), and these two cell clusters were all cells with a high positive rate of PD-L1." (PMID 39991571, 2025). "SLPI, WFDC2, WFIKKN2, and WFDC1 consistently showed low expression across tumor types, whereas WFDC5, WFDC3, and WFIKKN1 displayed heterogeneous expression profiles." (PMID 40350979, 2025). "Statistical analysis showed significant tumor-specific upregulation of WFDC1, WFDC2, WFDC3, SLPI, PI3, and ANOS1 (P < 0.0001), while WFIKKN1 was notably downregulated in neoplastic tissues (P < 0.0001)." (PMID 40350979, 2025).
tumor (continued). "The expression distribution of malignant markers of OC (WFDC2 and PAX8) and pathological identification enabled us to determine the aggregated areas of tumor cells." (PMID 39773329, 2025). "Interestingly, WFDC2 levels after cycle 4 were not significantly different from baseline levels, which may indicate that, in some patients, WFDC2 levels stabilize or decline after initial elevation, possibly reflecting immune activation or reduced tumor burden in responders." (PMID 40723266, 2025). "CD24, CLDN3, WFDC2, and TACSTD2 genes were present in all the tumour clusters of all samples, and the genes C1orf194, C20orf85, MS4A8, ODF3B, RSPH1, and TPPP3 appear to be co‐expressed." (PMID 41160707, 2025). "WFDC2, along with NAPSA and MUC1, was upregulated in PD-L1–positive tumor cells, suggesting its potential role in immune evasion." (PMID 40723266, 2025). "Greater increases in WFDC2 levels were significantly correlated with shorter OS (p = 0.002), shorter PFS (p = 0.037), and tumor progression (p = 0.003)." (PMID 40723266, 2025). "MUC16 and WFDC2 are known markers for HGSOC cells and Stereo-seq data demonstrated the expression of these two genes in the tumor compartment of the HGSOC sample." (PMID 38473208, 2024). "Of the overlapping set of proteins, the levels of WFDC2, S100P, CD55, MDK, THBS2, and MFAP2 were more than 2-fold higher in PDAC compared with tumor-adjacent tissue in our data." (PMID 36923555, 2022). "The regression model for the observed tumor grade used a combination of only two proteins, CCL23 and WFDC2." (PMID 30451357, 2019). "However, although WFDC2 is upregulated in LUAD, this same increase in expression is not observed in lung squamous cell carcinoma (LUSC), suggesting a tumor subtype-specific role." (PMID 40727473, 2025). "We observed that WFDC2 expression was significantly downregulated in tumor tissues compared with non-tumor tissues." (PMID 32678075, 2020). "Interestingly, in patients with gastrointestinal tumors, it has been found that the expression of genes, such as TLRs, WFDC2, TTLL12, THRA, and EPHB3, which can trigger an immune response and release of pro-inflammatory factors and thus accelerate tumor cell invasion, is disturbed." (PMID 38243957, 2025). "The strong correlation observed in LUAD highlights the potential of WFDC2 as a biomarker for this subtype, whereas the lack of significant correlations in other cancers suggests that its prognostic value may be limited to specific tumor types." (PMID 40727473, 2025). "However, this does not dispel all doubts that there could be pre‐tumour cells in control 3, supported by the presence of CLDN3 and WFDC2 which are two markers always present in tumour clusters." (PMID 41160707, 2025).
cancer (191 papers, 2006 to 2026). A tumor composed of atypical neoplastic, often pleomorphic cells that invade other tissues. "Collectively, these findings suggest that WFDC2 plasma concentration is associated with OS in a cancer-type-specific manner and serves as an independent prognostic biomarker in specific cancer types." (PMID 40727473, 2025). "Given these gaps, further investigation into WFDC2 as both a diagnostic and prognostic biomarker is essential for advancing cancer detection and treatment strategies." (PMID 40727473, 2025). "Human epididymis secretory protein 4 (HE4) is a secreted glycosylated protein encoded by the WAP four-disulfide core domain 2 (WFDC2) gene, located on a chromosome 20 segment that is frequently amplified in many cancers." (PMID 26030627, 2015). "WAP four-disulfide core domain 2 (WFDC2), the gene encoding HE4, is located on chromosome 20, in a segment frequently amplified in many cancers (breast, ovarian, colon, pancreas, and lungs)." (PMID 26030627, 2015). "Notably, WFDC2, a pro-fibrotic proteinase inhibitor involved in innate immunity, was overexpressed in various cancers and associated with smoking." (PMID 40928391, 2026). "GSEA showed that WFDC2 was associated with the metastatic phenotype in various cancers." (PMID 32678075, 2020). "Therefore, WFDC4, along with WFDC2—which affects multiple cancer-associated signaling pathways—could be considered as potential therapeutic targets." (PMID 39296934, 2024). "In this pilot study, we longitudinally examined early changes in serum sPD-1, sPD-L1, and WFDC2 levels in patients with advanced cancer receiving anti-PD-1 antibodies." (PMID 40723266, 2025). "Research into the biomarker potential and functional roles of WFDC2 in these cancers remains limited, with only a few studies available." (PMID 40727473, 2025). "Understanding cancer-type-specific molecular characteristics and differences in the TME is also crucial for comprehending the role of WFDC2 in cancer progression." (PMID 40727473, 2025). "The prognostic impact of WFDC2 expression varies by cancer type, as indicated by the Kaplan-Meier analysis of database studies." (PMID 40727473, 2025). "Plasma WFDC2 concentrations were significantly elevated in patients with cancer compared with healthy donors (p < 0.0001, Wilcoxon test), suggesting its potential utility as a diagnostic biomarker." (PMID 40727473, 2025). "Collectively, these findings suggest that the prognostic significance of WFDC2 mRNA expression is dependent on the cancer type." (PMID 40727473, 2025). "Our results revealed differences in WFDC2 expression between healthy individuals and patients with cancer, with its impact on OS varying depending on the cancer type." (PMID 40727473, 2025). "WFDC2 is commonly upregulated in multiple cancer types and inflammatory diseases and WFDC12 is upregulated in some inflammatory diseases, suggesting their utility as a diagnostic and prognostic marker." (PMID 39296934, 2024). "Meanwhile, the JAK/STAT3 pathway can be inhibited by slicing WFDC2 which will suppress the cancer growth." (PMID 39296934, 2024). "While we were most interested in the cancerous squamous epithelial cells, the number of CECs (MUC5B, WFDC2) was larger than that of the cancer cells (TP63, KRT5, CDKN2A)." (PMID 35986392, 2022). "CA125 (MUC16), CEA (CEACAM5), and HE4 (WFDC2) are clinically established diagnostic and prognostic markers of CESC; high levels of these biomarkers suggest cancer progression and poor prognosis." (PMID 34539641, 2021). "Our results demonstrated that WFDC1 was attenuated while WFDC2 was significantly elevated in carcinoma tissue." (PMID 34301920, 2021). "A statistically significant difference in NPX levels between benign tumors and borderline tumors + cancer was found for only two proteins, HE4 (WFDC2) and CA125 (MUC16) (conservative cut-off p < 0.001, p-values adjusted with False Discovery Rate (FDR))." (PMID 33075095, 2020).
cancer (continued). "Both Meta3 and Meta4 cells have high expression of many key markers of metaplasia, such as Wfdc2, Mal2, and Gpx2, and cancer stem cell (CSC) marker genes, such as Cd44, CD133 (Prom1), and CD166 (Alcam)." (PMID 31804471, 2019). "Other studies have identified WFDC2 over expression in ovarian and other cancers and have focussed on its potential use as a cancer marker." (PMID 16600032, 2006). "Plasma WFDC2 levels were analyzed separately for each cancer type." (PMID 40727473, 2025). "Moreover, plasma WFDC2 levels were significantly higher in all cancer patient groups than in healthy donors (p < 0.0001)." (PMID 40727473, 2025). "In this study, we investigated the prognostic potential of WFDC2 (HE4) across various cancer types." (PMID 40727473, 2025). "Among identified potential biomarkers, WAP four-disulfide core domain 2 (WFDC2), also known as human epididymis protein 4 (HE4), has emerged as a promising candidate for cancer detection and monitoring." (PMID 40727473, 2025). "Conversely, SLPI, WFIKKN1, WFDC2, and WFDC1 demonstrated variable prognostic effects across cancer types, suggesting context-dependent, microenvironment-driven functional duality." (PMID 40350979, 2025). "Combined with the pan‐cancer analysis results, we selected HCC cells with downregulated expression of WFDC2 and EC cells with upregulated expression for comparative experiments." (PMID 38742362, 2024). "WFDC proteins have been found to be upregulated in many diseases, such as WFDC1, WFDC2, WFDC12, WFDC14 are upregulated in cancers, inflammatory diseases and so on." (PMID 39296934, 2024). "Interestingly, the serum level of WFDC2 was inversely correlated with cytotoxic T-cell infiltration, which indicated that WFDC2 might suppress proper T-cell trafficking and alter immunogenic responses in cancers." (PMID 35924143, 2022). "Other identified common up-regulated hub genes such as AKAP12, WFDC2, CALD1, and VSNL1 are related to drug resistance in various cancers although their involvement in oxaliplatin resistance in CRC was not identified and can be reported as protentional biomarkers which merits further exploration." (PMID 37535601, 2023). "Moreover, knockdown of WFDC2 decreased matrix metalloproteinase-2 (MMP-2) expression, both in vitro and in vivo, which indicated that WFDC2 may also contribute to cancer metastasis." (PMID 35924143, 2022).
benign tumors (32 papers, 2011 to 2025). "Of these, 15 proteins (PRSS8, MK, WFDC2 (HE4), IL-10, SOD2, PARP-1, hK11, PVRL4, MUC-16 (CA125), FR-alpha, CDH3, NTRK3, IL-8, IL-17C, EN-RAGE) were selected from the comparison between OC stage I–IV and benign tumors." (PMID 30519148, 2018).
kidney disease (12 papers, 2016 to 2025). "Consistent with data from clinical and animal models showing increased expression of WFDC2 in kidney diseases, we found that elevated plasma WFDC2 is associated with DKD progression." (PMID 38626182, 2025). "Administration of Wfdc2 neutralizing antibodies accelerated collagen I degradation and inhibited fibrosis in various mouse models of renal disease, demonstrating a profibrotic role for Wfdc246." (PMID 33436815, 2021). "We then validated that WFDC2 was significantly upregulated in many kidney diseases in human and kidney disease models in mouse from Nephroeseq database." (PMID 33644086, 2020). "WFDC2 has emerged as a promising clinical biomarker for kidney disease and fibrosis." (PMID 37626956, 2023).
adenocarcinoma (5 papers, 2006 to 2025). A common cancer characterized by the presence of malignant glandular cells. "We have also studied expression of WFDC2 in a range of pulmonary carcinomas and show that expression of the protein is associated with the majority of adenocarcinomas as well as in a significant minority of other lung tumour types." (PMID 16600032, 2006). "One of these studies also showed that some groups of non-adenocarcinoma lung tumours express increased WFDC2 RNA levels as measured by chip analysis." (PMID 16600032, 2006). "However, Wfdc18 was shown to promote apoptosis in mammary epithelial cells, and Wfdc2 could be involved in innate immunity and adenocarcinomas." (PMID 37408269, 2023). "Although we saw clear expression of WFDC2 in the majority of cases of adenocarcinomas, there were also a number of cases (21%) that were negative." (PMID 16600032, 2006).
infection (4 papers, 2019 to 2024). The state of being infected such as from the introduction of a foreign agent such as serum, vaccine, antigenic substance or organism. "Although it is unlikely that the PreF-antigen directly induced WFDC2 expression, it is possible that PreF-immunization skewed the calf’s innate responses towards protection against infection and exaggerated inflammation." (PMID 33803302, 2021).